SAMSN1 (SAM domain, SH3 domain and nuclear localization signals 1)
Description:
Negative regulator of B-cell activation. Down-regulates cell proliferation (in vitro). Promotes RAC1-dependent membrane ruffle formation and reorganization of the actin cytoskeleton. Regulates cell spreading and cell polarization. Stimulates HDAC1 activity. Regulates LYN activity by modulating its tyrosine phosphorylation (By similarity).
Synonyms: HACS1; NASH1; SASH2; SH3D6B; SLy2
Tractability: Antibody: the Human Protein Atlas places it where antibodies can reach. PROTAC: its protein half-life has been measured.
Gene: Protein-coding gene on chromosome 21 (14,485,228 to 14,658,821, reverse strand). Ensembl gene ENSG00000155307.
Subcellular location: Nucleus; Cytoplasm; Cell projection, ruffle
Subcellular location (Human Protein Atlas): Plasma membrane; Nucleoplasm
Gene Ontology:
Molecular function: phosphotyrosine residue binding; RNA binding
Biological process: negative regulation of adaptive immune response; negative regulation of B cell activation; negative regulation of peptidyl-tyrosine phosphorylation; regulation of intracellular signal transduction
Cellular component: nucleoplasm; nucleus; cytoplasm; cytosol; ruffle
Genetic constraint (gnomAD): Loss-of-function variants: 22 observed, 28.23 expected, observed/expected ratio (o/e) 0.78, 90% interval 0.56 to 1.11. The upper end of that interval is the gene's LOEUF score, 1.11, which puts it in group 4 of 6, group 1 being the genes least tolerant of losing a copy. Missense variants: 375 observed, 371.94 expected, observed/expected ratio (o/e) 1.01, 90% interval 0.93 to 1.1. Synonymous variants: 143 observed, 130.71 expected, observed/expected ratio (o/e) 1.09, 90% interval 0.95 to 1.26.
Homologues: Orthologues: macaque SAMSN1 (94% identical), chimpanzee SAMSN1 (94% identical), pig SAMSN1 (88% identical), dog SAMSN1 (88% identical), guinea pig SAMSN1 (85% identical), rat Samsn1 (82% identical), mouse Samsn1 (80% identical), rabbit SAMSN1 (66% identical), tropical clawed frog samsn1 (65% identical), zebrafish samsn1b (47% identical), zebrafish samsn1a (42% identical). Paralogues in human: SASH1 (42% identical), SASH3 (36% identical).
Diseases named in the same sentence as SAMSN1 in open-access papers:
SAMSN1 is named in the same sentence as 56 diseases in open-access papers, as found by Europe PMC text mining. Sharing a sentence is not in itself a finding about the gene and the disease. The quoted sentences say what the papers report.
myeloma (10 papers, 2009 to 2023). "The protein SAMSN1 was recently identified as a putative tumor suppressor in multiple myeloma, with re‐expression of Samsn1 in the 5TGM1/KaLwRij murine model of myeloma leading to a near complete abrogation of intramedullary tumor growth." (PMID 32923989, 2020). "Restoration of Samsn1 expression in the C57BL6/KaLwRij‐derived myeloma cell line 5TGM1 led to a remarkable abrogation of the capacity of these cells to produce bone marrow (intramedullary) tumors in vivo." (PMID 32923989, 2020). "The rejection of Samsn1‐expressing 5TGM1 myeloma cancer cells is characteristic of the classic elimination and equilibrium phases of control of cancer by immune surveillance." (PMID 32923989, 2020). "The 5TGM1 myeloma cell line, originally isolated from a myeloma-bearing KaLwRij mouse, was confirmed as Samsn1-null." (PMID 26020268, 2015). "SAMSN1 (HACS1) was first cloned on the basis of its differential expression in multiple myeloma with low expression in human myeloma cell lines." (PMID 26020268, 2015). "Compared to wild-type, Samsn1-/- M2 macrophages significantly increased the growth of myeloma tumors." (PMID 26020268, 2015). "The SAMSN1 has been reported to be highly expressed in various human malignancies including myeloma, acute myeloid leukemia, and lymphoma." (PMID 24690091, 2014). "Xenografts were conducted to ascertain whether SAMSN1 expression affected the intramedullary growth of human MM cells in long bones, and/or whether SAMSN1 would reduce the ability of the myeloma cells to form distal metastases." (PMID 32923989, 2020). "While SAMSN1 is not deleted in human MM, components of a SAMSN1 pathway appear likely to involved in myeloma susceptibility and/or disease progression." (PMID 26020268, 2015). "To further investigate whether SAMSN1 participates in human myeloma, we queried plasma-cell SAMSN1 gene expression in patient samples." (PMID 26020268, 2015). "In order to discover whether the tumor suppressor properties of Samsn1 were also apparent in human myeloma cells, a combination of CRISPR‐Cas9 mutation and viral transgenesis was used to generate 4 different human myeloma cell lines (HMCLs) with matched SAMSN1‐high and SAMSN1‐low/null expression." (PMID 32923989, 2020). "We next tested whether Samsn1 expression played a role in fully transformed myeloma cells." (PMID 26020268, 2015). "Samsn1, alias HACS1, NASH1, and SLy2, is mainly expressed in normal hematopoietic tissues and malignant tumors of the hematopoietic system, such as multiple myeloma, lymphoma, etc., and also in gallbladder, heart, lung, brain, and other tissues." (PMID 37091532, 2023). "Two additional highly homologous proteins have been described: SLY2, also termed SAMSN1/NASH1/HACS1, is more broadly expressed in haematopoietic tissues, endothelial cells and myeloid leukemias and myelomas." (PMID 19604361, 2009). "Altering SAMSN1 expression in these human myeloma cells did not affect the capacity of the cells to establish either primary or metastatic intramedullary tumors when administered intratibially into immune deficient NSG mice." (PMID 32923989, 2020). "Surprisingly, the mutations we found in this strain, including a deletion of the Samsn1 (Hacs1) gene, are not restricted to B-cells, but also affect macrophages and other bone marrow populations to support myeloma development." (PMID 30453544, 2018). "SAMSN1 regulates HDAC1 activity and is known as a tumor suppressor in multiple myeloma." (PMID 28714904, 2017). "We found significant gene expression differences between C57BL/6 and KaLwRij BMSCs, a myeloma-supportive cell type in the tumor microenvironment that does not express Samsn1." (PMID 26020268, 2015).
glioblastoma multiforme (8 papers, 2013 to 2023). "High expression of Samsn1 was associated with high mortality in glioblastoma multiforme, but Samsn1 was found to be expressed at significantly low levels in HCC." (PMID 38139000, 2023). "But the SAMSN1 is over-expressed in glioma and the high expression of SAMSN1 is a significant risk factor for the progression of glioblastoma multiforme." (PMID 28344339, 2017). "SAMSN1 was found to be expressed highly in glioblastoma multiforme, and high expression was a significant risk factor for poor survival." (PMID 27358011, 2016). "Undesirable responses involving upstream regulators of mouse genes were also observed, including activation of SAMSN1, which is associated with poor prognosis for survival in glioblastoma." (PMID 25952672, 2015). "By contrast, another activated upstream regulator, SAMSN1, which is highly expressed in glioblastoma, is associated with poor prognosis for survival." (PMID 25952672, 2015). "High expression of SAMSN1 was found to be a strong risk factor for the progression free survival and overall survival of glioblastoma multiforme." (PMID 24278465, 2013). "In addition, SAMSN1 was found to be closely related to glioblastoma multiforme, and upregulated SAMSN1 was a dangerous factor for patients with glioblastoma multiforme." (PMID 37786523, 2023). "It has been reported that SAMSN1 was elevated and correlated with adverse clinical outcomes in glioblastoma multiforme (GBM)." (PMID 35756681, 2022).
hepatocellular carcinoma (5 papers, 2018 to 2024). A malignant tumor that arises from hepatocytes. "Our results also demonstrate that the gene OSBP2 functions in cell proliferation, while SAMSN1 is associated with the malignant hepatocellular carcinoma phenotype." (PMID 29187421, 2018). "Additionally, low SAMSN1 protein production in hepatocellular carcinoma and gastric cancer was associated with decreased overall survival and expanded tumor size." (PMID 39015503, 2024). "Furthermore, SAMSN1 mRNA expression was found to be lower in cancerous tissues compared to normal adjacent tissue from gastric cancer and hepatocellular carcinoma patients." (PMID 32923989, 2020). "Low SAMSN1 expression in these cancers was found to be associated with increased tumor size and decreased overall survival, suggesting that SAMSN1 may also be a tumor suppressor gene in gastric cancer and hepatocellular carcinoma." (PMID 32923989, 2020).
lung carcinoma (5 papers, 2020 to 2023). "The first description of reduced SAMSN1 expression was in lung cancer, in which loss of heterozygosity at 21q21, the chromosomal location of the SAMSN1 gene, is a common abnormality." (PMID 32923989, 2020). "The human SAMSN1 gene is located on chromosome 21q11-21, a region associated with heterozygous deletions frequently found in lung cancer cells, suggesting that SAMSN1 may be a tumor suppressor." (PMID 38139000, 2023). "SAMSN1, which is located in a common genomic deletion region in lung cancer and is associated with B cell differentiation, may act as a suppressor gene in lung cancer." (PMID 36969247, 2023). "Lastly, SAMSN1 is expressed in healthy lung epithelial cells but not in lung cancer cells." (PMID 32937976, 2020).
lymphoma (3 papers, 2014 to 2023). A malignant (clonal) proliferation of B- lymphocytes or T- lymphocytes which involves the lymph nodes, bone marrow and/or extranodal sites. "SAMSN1, typically highly expressed in lymphomas, is a splice variant of HACS1 which promotes RAC1-dependent membrane ruffle formation." (PMID 34570764, 2021). "By knocking down SAMSN1 in lymphoma cell line did not affect the cancer cell proliferation." (PMID 24690091, 2014).
myeloid leukemia (3 papers, 2009 to 2019). A clonal proliferation of myeloid cells and their precursors in the bone marrow, peripheral blood, and spleen. "We observed highly specific regulatory relationships around SAMSN1 in K562, a myelogenous leukemia cell line, revealing a strong association between its expression and accessibility of CREs." (PMID 30692544, 2019).
acute myocardial infarction (2 papers, 2021 to 2023). Necrosis of the myocardium, as a result of interruption of the blood supply to the area. "A differential expression of the platelet gene SAMSN1 has been reported to be related to myocardial infarction, and SMSN1 was also associated with coronary atherosclerosis." (PMID 34925639, 2021).
Alzheimer disease (2 papers, 2020 to 2023). A progressive, neurodegenerative disease characterized by loss of function and death of nerve cells in several areas of the brain leading to loss of cognitive function such as memory and language. "Moreover, in Alzheimer's disease, using GWAS, SAMSN1 was found to be below the genomewide significance threshold, and it was significantly upregulated when exposed to amyloid β‐protein." (PMID 37786523, 2023).
atherosclerosis (2 papers, 2017 to 2022). A disease characterized by the build-up of fatty material and calcium deposition in the arterial wall resulting in partial or complete occlusion of the arterial lumen. "All three were intergenic; the most significant interaction was in a regulatory region associated with SAMSN1, a gene previously associated with atherosclerosis and B cell activation." (PMID 28355232, 2017). "Thus, an association has been established between several stretch-specific miR-1183 targets and cardiac remodeling, such as: KCNA3 with diabetic cardiomyopathy, MED23 with CHD, SAMSN1 with atherosclerosis, CCND1 with myocardial ischemia-reperfusion injury, and MCOLN3 with atrial fibrillation." (PMID 35805966, 2022).
cerebral malaria (2 papers, 2023 to 2025). A sequestration of Plasmodium falciparum in the brain, which can cause coma and/or seizures. "A recent study applied network analysis and differential expression to whole-blood profiles, highlighting nine key host genes (including MBP, SAMSN1, PSMF1, SLC39A8) strongly linked to cerebral malaria." (PMID 41002937, 2025). "In the nervous system, SAMSN1 was related to cerebral malaria by using genomic analysis of host gene responses to cerebral Plasmodium falciparum malaria." (PMID 37786523, 2023).
colorectal cancer (2 papers, 2020 to 2023). A primary or metastatic malignant neoplasm that affects the colon or rectum. "In addition, ulcerative colitis patients with colon cancer were found to have significantly lower expression of SAMSN1 compared to those patients without cancer, suggesting that SAMSN1 may inhibit the transition from pre‐neoplastic lesions to overt malignancy in colorectal cancer." (PMID 32923989, 2020).
glioma (2 papers, 2013 to 2017). A benign or malignant brain and spinal cord tumor that arises from glial cells (astrocytes, oligodendrocytes, ependymal cells). "The results showed that the expression of SAMSN1 was increased in all grades of glioma compared with that in normal brain tissues." (PMID 24278465, 2013). "Next, we analyzed the expression of SAMSN1 by tissue microarray with a larger sample size of 288 glioma specimens and normal brain tissues, with detailed and reliable clinical follow-up data." (PMID 24278465, 2013). "The results indicated that the expression of SAMSN1 was higher in glioma than that of the normal brain group." (PMID 24278465, 2013). "In the present study, by analyzing the gene chip, the TCGA dataset, and the tissue microarray data, we have found a gene named SAMSN1 that is highly expressed in glioma, and indicates prognostic significance in GBM." (PMID 24278465, 2013). "Compared to normal brain, the expression of SAMSN1 was 1.53 ± 1.04 (p >0.05) in low-grade glioma and 2.05 ± 1.53 (p=0.037) in high-grade glioma." (PMID 24278465, 2013). "Grade II glioma exhibited a pivotal elevation of nuclear SAMSN1 expression compared to all other groups (p<0.05)." (PMID 24278465, 2013). "Gene and large sample tissue microarrays showed high expression of SAMSN1 in glioma particularly in GBM." (PMID 24278465, 2013). "Survival analysis by Kaplan-Meier estimates in each grade of glioma was stratified by SAMSN1 expression." (PMID 24278465, 2013). "Another intriguing question is that SAMSN1 expressed highly in all grades of glioma, but why was it only related to the prognosis of GBM?" (PMID 24278465, 2013). "In this study, we found that the SAMSN1 gene was over-expressed in glioma as compared with that found in normal brains." (PMID 24278465, 2013). "At last, we detected the expression of SAMSN1 in large numbers of glioma and normal brain tissue samples using Tissue Microarray (TMA)." (PMID 24278465, 2013). "Survival analysis based on the TCGA GBM data matrix and TMA multi-grade glioma dataset found that SAMSN1 expression was closely related to the prognosis of GBM, either PFS or OS (P<0.05)." (PMID 24278465, 2013). "It was found that in normal brains, SAMSN1 expressions were at a low level, whereas in low and high-grade glioma, SAMSN1 was found to be expressed at high levels." (PMID 24278465, 2013). "We first analyzed the expression of SAMSN1 in glioma and normal brain tissues by our gene chip data." (PMID 24278465, 2013). "Survival analysis stratified by SAMSN1 expression was made by Kaplan-Meier estimates in each grade of glioma." (PMID 24278465, 2013). "For the expansion of the sample size, it was possible to analyze the expression of SAMSN1 and make survival analysis in glioma of each grade." (PMID 24278465, 2013). "With the expression data of SAMSN1 and 68 other genes, high-grade glioma could be classified into two groups with clearly different prognoses." (PMID 24278465, 2013). "It was also shown that the expression of SAMSN1 might be a prognostic factor in higher grade glioma." (PMID 24278465, 2013). "Sixty-nine genes (SAMSN1 included) were filtered out, following which the expression of SAMSN1 could be applied to the prognosis of high grade glioma and classified into two groups." (PMID 24278465, 2013). "SAMSN1 is over-expressed in glioma as compared with that found in normal brains, especially in GBM." (PMID 24278465, 2013). "Whether a low grade glioma which highly expressed SAMSN1 is more likely to progress into secondary GBM?" (PMID 24278465, 2013). "Furthermore, survival analysis also didn’t find any correlations between the nuclear expression of SAMSN1 and the prognosis of any subtype of glioma." (PMID 24278465, 2013). "The objective of this analysis was to study the expression pattern of SAMSN1 in glioma tissues, and attempt to find preliminarily evidence on whether its expression is correlated with the clinical prognosis of glioma patients." (PMID 24278465, 2013).
glioma (continued). "The role of SAMSN1 in glioma remains unclear, and to the best of our knowledge, there has not been a prior report of its functional expression and prognostic value in glioma." (PMID 24278465, 2013). "Affymetrix and Arrystar gene microarray data in the setting of glioma was analyzed to preliminarily study the expression pattern of SAMSN1 in glioma tissues, and Hieratical clustering of gene microarray data was performed to filter out genes that have prognostic value in malignant glioma." (PMID 24278465, 2013). "Thus it is reasonable to speculate that there might be some important relationships between the expression of SAMSN1 and glioma." (PMID 24278465, 2013). "In nuclear, the scores of SAMSN1 expression in normal brain and WHO grade I – IV glioma were 0.00 ± 0.00, 0.00± 0.00, 0.37 ± 1.03, 0.03± 0.16, and 0.06±0.38, respectively." (PMID 24278465, 2013). "In cytoplasm, the scores of SAMSN1 expression in normal brain and WHO grade I – IV glioma were 1.69 ± 1.30, 5.11 ± 3.33, 5.66 ± 2.93, 5.60 ± 3.12, and 5.86 ± 3.02, respectively." (PMID 24278465, 2013). "Therefore, the meaning for the SAMSN1’s subcellular distributions in glioma remains unclear." (PMID 24278465, 2013). "In our study, we found that the SAMSN1 protein was distributed mainly in the cytoplasm of both normal brain and glioma cell." (PMID 24278465, 2013). "Although there has been no previous report about the action of SAMSN1 in glioma, a former study has shown that SAMSN1 expression can be increased in B lymphocyte by IL-4 stimulation through both STAT6 and PI3k/PKC/NF-κB pathways." (PMID 24278465, 2013). ".Because of the limited sample size, it was not possible to compare the SAMSN1 expressions of each grade glioma." (PMID 24278465, 2013). "At last, we detected the expression of SAMSN1 in large numbers of glioma and normal brain tissue samples using Tissue Microarray (TMA); the purpose of this latter analysis was to further clarify the expression pattern of SAMSN1 and its prognostic significance in each grade of Glioma." (PMID 24278465, 2013). "Although SAMSN1 sometimes expressed in nucleus (8.3% of all glioma cases, 4.3% in GBM), high nuclear expression was very rare, only 0.7% of all glioma cases, compared with 60.1% glioma with a high cytoplasmic expression of SAMSN1." (PMID 24278465, 2013). "Therefore, SAMSN1 is a valuable molecular index for prediction of GBM prognosis, and thus might represent a latent target for gene therapy in the setting of glioma." (PMID 24278465, 2013). "However, interestingly, the SAMSN1 expression was not related to the prognosis of other types of glioma except for the GBM." (PMID 24278465, 2013).